VCAM1 (vascular cell adhesion molecule 1)
Diseases named in the same sentence as VCAM1 in open-access papers (continued):
Sharing a sentence is not in itself a finding about the gene and the disease.
Sepsis (continued). "However, how Kupffer cell activation affects adhesion molecules (ICAM-1 and VCAM-1) in sepsis has not been determined." (PMID 38254684, 2024). "VCAM-1 protein expression in pulmonary microvascular beds did not change in this sepsis model." (PMID 39200137, 2024). "VCAM-1 protein, on the other hand, was constitutively expressed mainly in microvessels and in a scattered manner in alveolar capillaries, which did not change during sepsis development." (PMID 39200137, 2024). "The serum levels of soluble VCAM-1 and ICAM-1 correlate with organ dysfunction in sepsis, and these clinical observations support the hypothesis that soluble adhesion molecules are involved in the pathogenesis of sepsis." (PMID 37048076, 2023). "Interestingly, endothelial activation during sepsis, as indicated by high circulating levels of intercellular adhesion molecule-1 (ICAM-1), vascular cell adhesion molecule-1 (VCAM-1), E-selectin, P-selectin, and vWF, is correlated with disease severity and mortality." (PMID 37081895, 2023). "In addition, the protein levels of VCAM-1 (576.3 ± 11.31 vs. 2360 ± 19.72, p < 0.05) and ICAM-1 (43.66 ± 1.69 vs. 129.2 ± 1.30, p < 0.05) were also significantly higher in the supernatant of sepsis serum group than in controls." (PMID 35145983, 2022). "Considering the ability of MMP8 in upregulating the expression of VCAM-1, and the over adhesion of leukocyte to endothelium in sepsis, we hypothesized that sepsis serum promotes leukocyte adhesion to endothelium via MMP8 in sepsis." (PMID 35145983, 2022). "In this study, the protein levels of vascular cell adhesion molecule 1 (VCAM1) and intercellular adhesion molecule 1 (ICAM1) in the lung tissue of DEFA1/DEFA3-HCN mice were significantly higher than those of DEFA1/DEFA3-LCN mice and WT mice 24 hours after the onset of disease septicemia." (PMID 36776394, 2022). "Scaffold preparation did not induce secretion of VCAM-1, which mediates the attachment of circulating blood leukocytes, potentiates an inflammatory reaction in vivo and initiates, in infection, the early stages of sepsis." (PMID 33149936, 2020). "Licochalcone C played a vital role in sepsis-induced inflammation through repressing NF-κB translocation and several kinds of downstream molecules, including iNOS, intercellular adhesion molecule-1 (ICAM-1), as well as vascular cell adhesion molecule-1 (VCAM-1)." (PMID 32256642, 2020). "Furthermore, soluble fragments of VCAM-1 and ICAM-1 are correlated with the severity of sepsis." (PMID 30873161, 2019). "Shedding of the endothelial adhesion molecules vascular adhesion molecule 1 (VCAM-1) and intercellular adhesion molecule 1 (ICAM-1) has been shown to be an important process in controlling leucocyte migration and to enhance cytokine release during sepsis in the liver." (PMID 30873161, 2019). "Therefore, it is possible that α2A-AR blockade attenuates sepsis-induced myocardial dysfunction through inhibiting cardiac VCAM-1 expression, which was independent of NE-stimulated α1-AR pathway." (PMID 29615637, 2018). "A similar phenotype was observed in a model of sepsis, where whole-body PTP1B deletion not only improved survival rate in response to septic shock, but decreased cardiac dysfunction and the expression of pro-inflammatory markers such as IL1β, ICAM-1, VCAM-1, COX-2 and iNOS." (PMID 28899902, 2017). "Therefore, miR-23b may play a significant role in the pathogenesis and progression of sepsis by inhibiting the expression of inflammatory factors, including NF-κB, TNF-α, IL-6, ICAM-1, E-selectin and VCAM-1." (PMID 25780398, 2015). "Furthermore, the tempting sequential concept of Ang-2 as a primer for excess endothelial adhesion molecule (e.g. ICAM-1, VCAM-1, and E-selectin) expression in sepsis has not been investigated in human sepsis." (PMID 19416526, 2009).
Sepsis (continued). "We determined the protein expression of ICAM-1 and VCAM-1 and their immunoreactivity in liver and lung tissues from an experimental CLP sepsis mice model with and without GdCl3 pretreatment to compare the effects of GdCl3 on these tissues." (PMID 38254684, 2024). "A comparison of patients with sepsis with and without AKI indicated that the AKI patients had greater expression of CD62L, CD62E and VCAM-1." (PMID 36333626, 2023). "Furthermore, a significant correlation between SAPS II and the expression of VCAM-1 (r = 0.61, p = 0.01) and E-selectin (r = 0.59, p = 0.02) by CD34+/CD133+-stem cells of sepsis survivors could be detected, but not of non-survivors." (PMID 29601599, 2018).
melanoma (107 papers, 2005 to 2026). A malignant, usually aggressive tumor composed of atypical, neoplastic melanocytes. "This supports previous reports of VEGF reduction of TNF-α-induced upregulation of ICAM-1 and VCAM-1 in cultured ECs and tumour-associated ECs isolated from melanoma tissues." (PMID 40650058, 2025). "A recent study found that overexpression of integrin α4β1 on primary melanoma cells is associated with increased bone turnover through interaction with constitutively expressed VCAM-1 in bone marrow stromal cells." (PMID 33879860, 2021). "FAK inhibition reduced VCAM-1 expression both in lymph nodes and human dermal lymphatic ECs, which was associated with reduced lymph node metastasis and melanoma-EC attachment." (PMID 32514188, 2020). "The over-expression of integrin α4β1 on primary melanoma cells was found to be associated with increased bone metastasis, probably via interaction with VCAM-1, which is constitutively expressed on bone marrow stromal cells." (PMID 29703238, 2018). "In addition, the overexpression of integrin α4β1 on primary melanoma cells appears to be associated with increased bone metastasis, probably through the interaction with VCAM-1, which is constitutively expressed on bone marrow stromal cells." (PMID 39274345, 2024). "In further support of the important role of the tumor expression of VLA-4 in metastatic potential, over-expression of VLA-4 is linked to tumor progression in melanoma, endometrial cancer, neuroblastoma, pancreatic cancer and leukemia, where VCAM-1 is also up-regulated." (PMID 36497180, 2022). "Additionally, the protein expression levels of metastasis-associated genes (such as MMP2/9, ICAM-1 and VCAM-1) in melanoma cells were suppressed by CLQ treatment." (PMID 31138783, 2019). "In this context it is interesting to note that the therapeutic reduction of cell-cell adhesion by inhibition of VLA-4 (α4β1 integrin; ligand of endothelial VCAM-1) in multiple sclerosis patients may elevate the risk to develop melanoma." (PMID 29348824, 2017). "B16 melanoma cell adhesion to activated bEnd.3 endothelial monolayers or immobilized VCAM-1 were analyzed under defined shear flow using a parallel-plate chamber." (PMID 42074287, 2026). "In combination with bevacizumab, anti-CTLA-4 enhanced tumor infiltration by promoting E-Selectin, ICAM-1 and VCAM-1 at the surface of melanoma cells." (PMID 40071851, 2025). "Another study also found interactions between melanoma-derived EVs and lymphatic EC, this time mediated by vascular cell adhesion molecule 1 (VCAM-1)." (PMID 39866233, 2025). "Recent studies of T cell recruitment in other intracranial tumor models (i.e., melanoma) found negligible VCAM-1+ endothelial or pericyte populations." (PMID 40244705, 2025). "ITGA4 expression on melanocytes allows adhesion to vascular cell adhesion molecule 1 (VCAM-1) on lymphatic endothelial cells and has been shown to facilitate melanoma lymph node metastases in a mouse model." (PMID 40717170, 2025). "A recent study highlighted the distinctive features of melanoma by identifying a subset of VCAM-1+ TAMs using scRNA-seq in a B16F10 melanoma model." (PMID 40918451, 2025). "In this study, we first confirmed that cell surface expression of VCAM-1 and melanoma cell adhesion were comparable between PECAM-1-ko and PECAM-1-wt pMBMECs." (PMID 37894438, 2023). "Treatment with rm-IL-17A led to increased mRNA expression of key T cell chemokines such as CXCL9–CXCL11, adhesion molecules ICAM1 and VCAM1 and IL-17-dependent cytokines in melanoma cells." (PMID 37525015, 2023). "Vascular cell adhesion molecule-1 (VCAM-1) was also overexpressed in HHSEC as a result of co-culturing in three melanoma cell lines." (PMID 37240247, 2023). "For decades, VLA-4 (α4β1) has been a known marker of melanoma cells, and its role in binding to VCAM-1 on EC and metastasis is well documented, but the majority of these studies focused on lung metastasis and were based on ECs from outside the CNS." (PMID 37173970, 2023).
melanoma (continued). "IL-18 can also promote liver metastasis of melanoma cells by regulating the expression of vascular cell adhesion molecule-1 and the adhesion of melanoma cells." (PMID 36707882, 2023). "In the case of melanoma, the endothelial expression levels of VCAM-1 were shown to correlate with metastatic pattern." (PMID 37173970, 2023). "Previously, it was described that IL-18 is able to increase the expression of VCAM-1 in the hepatic sinusoidal epithelium, promoting the adherence of melanoma cells." (PMID 37240247, 2023). "Specifically, VCAM-1 has been reported to be over-expressed on many types of cancers, such as breast, gastric, ovarian and melanoma, and purported to play a role in the metastatic progression of these tumors." (PMID 36497180, 2022). "Upregulation of genes involved in macrophage recruitment (Ccl2), cell adhesion and migration (Vcam1, Stab1, Lyve1), angiogenesis (Vegfa) and cell proliferation/survival (Igf1) all suggested a phenotype similar to TAMs of s.c. melanoma." (PMID 36241867, 2022). "In the melanoma brain metastasis samples, a statistically significant inverse relationship was evident between the concentration of VCAM-1–positive vessels and distance from the tumor border (P = 0.0422)." (PMID 35312755, 2022). "The contribution of VCAM-1 in tumor metastatic potential was first described in adhesion of melanoma cells to the endothelium." (PMID 36497180, 2022). "The α4β1 integrin expressed by melanoma cells binds vascular cell adhesion molecule 1 (VCAM‐1) expressed by lymph node ECs." (PMID 32761606, 2021). "Melanoma cells that express integrin α4β1 tend towards lymph node metastasis through binding to vascular cell adhesion molecule-1 (VCAM-1) on endothelial cells." (PMID 34207884, 2021). "The same proteins, each expressed by the counter cell (α4β1 integrin by ECs and VCAM‐1 by melanoma cells), also play a functional role in melanoma adhesion to lymph node ECs." (PMID 32761606, 2021). "With murine melanoma cells, the inhibition of spreading by VCAM-1 observed with nanostructured matrices also corresponded to the function of these melanoma cells observed in vivo." (PMID 31991896, 2020). "Melanoma cells also target endothelial VCAM-1 through tumor-derived SPARC, which induces paracellular endothelial permeability." (PMID 33172202, 2020). "Integrin α4β1 (also known as very late antigen-4; VLA-4) binds to vascular cell adhesion protein-1 (VCAM-1) in B16F10 melanoma cells, so that cancer cells adhere to endothelial cells." (PMID 32538273, 2020). "VLA‐4 was shown to be essential for adherence of melanoma cells to VCAM‐1‐expressing endothelial cells, with clones of melanoma cells expressing VLA‐4 displaying increased metastases in IL‐1‐treated mice." (PMID 33210465, 2020). "Our recent study showed that lymph node ECs express VCAM-1, which is important for melanoma-lymphatic EC interactions." (PMID 32514188, 2020). "The up-regulation of VCAM1 occurs in systemic oxidative stress, myeloperoxidase, autoimmune disease and particularly in malignant melanoma." (PMID 32900003, 2020). "The importance of VLA-4 expressed on melanoma cells that mediates adhesion to endothelial VCAM-1 to promote extravasation is also shown in mouse models following intravenous injection of melanoma cells." (PMID 33172202, 2020). "Blocking VCAM-1 impedes melanoma-induced endothelial permeability in vitro and lung metastasis in a mouse model following intravenous injection." (PMID 33172202, 2020). "For instance, administration of IL-18BP significantly suppressed melanoma cell metastasis to the liver by preventing IL-18-induced expression of adhesion molecules such as vascular cell adhesion molecule-1 (VCAM-1) on hepatic sinusoidal endothelial cells." (PMID 31231372, 2019). "Recently, one study assessed the molecular relationship between OSA and melanoma, concluding that OSA increased circulating VCAM-1 levels in melanoma patients." (PMID 31530881, 2019).
melanoma (continued). "High levels of integrin α4ß1 have been identified on A375M melanoma cells, allowing them to adhere to VCAM-1 on the vascular endothelium." (PMID 30657059, 2019). "OGD exposed h-EC also displayed enhanced adhesion of metastatic melanoma cells, which was reduced by blocking VCAM-1." (PMID 31024232, 2019). "Animals that received DABK had a lower number of melanoma colonies established in the lungs, decreased expression of the vascular cell adhesion molecule 1 (VCAM-1), and higher number of CD8+ T cells recruited to the lungs." (PMID 31607931, 2019). "On the other hand, integrin α4β1 is also expressed on LECs in the lymph nodes, and activated α4β1 on LECs in lymph nodes plays a functional role in capturing VCAM-1+ metastatic melanoma cells." (PMID 29703238, 2018). "Aberrant VCAM-1 expression occurs in various solid tumor, including breast tumor, melanomas, and renal carcinoma." (PMID 29670110, 2018). "Integrin α4 can dimerize with β1 and β7 subunits, forming two isoforms, α4β1 (VLA-4) and α4β7, in which α4β1 is especially important for the adhesion of melanoma cells to LECs via binding to VCAM-1." (PMID 29703238, 2018). "On the one hand, α4β1 is expressed on some melanoma cells and helps them to attach to the VCAM-1+ LECs." (PMID 29703238, 2018). "In vitro, melanoma cell lines are also able to adhere to endothelial cells in a process involving αvβ3 integrin, α4β1-integrin, endothelial VCAM-1, Lu-ECAM-1, as well as the chemokines, including CXCL12." (PMID 28253287, 2017). "Melanoma cells express the ligand very late antigen (VLA)-4 (α4β1) which binds vascular cellular adhesion molecule (VCAM)-1, an integrin receptor displayed on the surface of endothelial cells." (PMID 25225982, 2014). "We have previously shown that the VLA-4/VCAM-1 adhesion event leads to the disassembly of VE-cadherin, which facilitates melanoma extravasation." (PMID 25225982, 2014). "Increased expression of VCAM-1 has been reported in various cancer cell types, including breast, gastric, renal carcinoma, and melanomas." (PMID 24052950, 2013). "Heparin was shown to inhibit the VLA-4 mediated melanoma binding to VCAM-1 substrates under dynamic conditions." (PMID 22505933, 2012). "Expression of integrin α4β1 (VLA-4) by B16F10 melanoma cells mediated their adhesion to endothelial cells through binding to VCAM-1." (PMID 22505933, 2012). "The specific VLA-4-mediated interaction with VCAM-1 on endothelium is required for melanoma cell adhesion and endothelial transmigration." (PMID 22505933, 2012). "Second, resveratrol inhibited IL-18-dependent expression of VCAM-1 by tumor-activated hepatic sinusoidal endothelium, preventing melanoma cell adhesion to the microvasculature." (PMID 21569399, 2011). "The mechanism was further supported by experiments revealing COX-2 overexpression in VEGF-treated melanoma cells and enhanced melanoma cell adherence to VCAM-1 induced by exogenous PGE2." (PMID 21867538, 2011). "In vitro, RVL completely abrogated the melanoma cell adhesion to tumor-activated HSE operated via VLA-4/VCAM-1 interaction." (PMID 21569399, 2011). "Interleukin-18 (IL-18) has been demonstrated in vivo and in vitro to promote liver metastasis by enhancing melanoma cell adhesion to the hepatic sinusoidal endothelial cells via microvascular VCAM-1 (vascular cell adhesion molecule-1) expression." (PMID 16336680, 2005). "Additionally, recent animal evidence reports that aerobic exercise improves tumor vasculature and increases VCAM-1 expression in two melanoma models, accompanied by enhanced immune mobilization." (PMID 41583457, 2025). "Given that recent studies have reported low fractions of VCAM-1+ cells in other intracranial malignancies (e.g., melanoma), this finding suggests that T cell recruitment and BBB trafficking dynamics may vary between cancer types." (PMID 40244705, 2025).